INS (insulin)
Diseases named in the same sentence as INS in open-access papers (continued):
Sharing a sentence is not in itself a finding about the gene and the disease.
Hyperglycemia (continued). "Infants with established NEC have a high prevalence of hyperglycemia and a worse outcome if hyperglycemic: increased levels of stress hormones and inflammatory cytokines secondary to NEC onset-induced transient insulin resistance that causes hyperglycemia, especially during the acute phase." (PMID 35267894, 2022). "Another study indicated that S100A6 could specifically promote calcium-stimulated insulin release, which is associated with hyperglycemia." (PMID 35432196, 2022). "This in turn decreases insulin concentrations and causes hyperglycemia." (PMID 36432781, 2022). "This impairment in insulin secretion from β-cells causes further hyperglycemia." (PMID 35562869, 2022). "In summary, it is likely that patients with genetically low insulin secretory capacity may be at an increased risk of development of diabetic ketoacidosis, and under sustained hyperglycemia." (PMID 36361703, 2022). "The levels of weight gain, hyperglycemia, and hyperinsulinemia were similar in both males and females of Lep KO mice, while significant differences are observed in only the metabolism associated with insulin signaling and lipid metabolism." (PMID 36548335, 2022). "Ageing-associated defects in insulin secretion have been demonstrated largely in studies where hyperglycemia has been induced by oral or intravenous glucose; they may not be present in response to protein administration." (PMID 35956288, 2022). "This enzyme catalyzes the conversion of inactive cortisone into the active hormone cortisol, a powerful glucocorticoid that acts as a contender of insulin action and stimulates gluconeogenesis in liver, leading to an increase in blood glucose levels and causing hyperglycemia." (PMID 35056159, 2022). "It causes hyperglycemia due to deficiencies in insulin secretion and/or insulin action." (PMID 36009274, 2022). "Hypercaloric diet caused hyperglycemia and hyperleptinemia that stimulated β-cell proliferation, this compensatory mechanism underwent structural modifications in β-cell in response to the circulating hyperglycemia, increasing insulin secretion." (PMID 34981743, 2022). "Hyperglycemia is a term used to describe a spectrum of metabolic disorders characterized by elevated blood glucose levels caused by abnormalities in insulin secretion, insulin sensitivity, or both." (PMID 35337139, 2022). "It reduces insulin efficiency in insulin-responsive tissues (muscle, fat, and liver), which conversely causes a decompensated increase in insulin and hyperinsulinemia, and then leads to chronic metabolic disorders (hyperglycemia, hypertension, hyperlipidemia, etc.)and inflammation." (PMID 36992743, 2022). "According to the authors, the lack of iodine in the organism induces the increase of TSH secretion in plasma, producing an antagonistic effect on insulin, generating hyperglycemia; which is associated with increased oxidative stress, which is a risk factor for placental abruption." (PMID 34033289, 2021). "In contrast, dexmedetomidine can excite α2A-adrenoreceptors of pancreatic β-cells and inhibit insulin secretion which may cause hypoinsulinaemia and a resultant state of hyperglycemia." (PMID 34555043, 2021). "Frequent consumption of sugar and high-sugar foods might increased the risk of PC by inducing frequent postprandial hyperglycemia, increasing insulin demand and decreasing insulin sensitivity." (PMID 34123787, 2021). "Last, we tested whether OCN administration is sufficient to alleviate hyperglycemia in mice with T1DM when insulin is deficient." (PMID 34489478, 2021). "It is unknown how many of the dogs in the present study received insulin, but insulin is rarely used to manage hyperglycemia associated with critical illness in our institution and hence the percentage is likely small." (PMID 33763464, 2021). "Over time, postprandial hyperglycemia may gradually cause pancreatic β-cell exhaustion, leading to a decrease in insulin secretion." (PMID 34062802, 2021).
Hyperglycemia (continued). "A relative deficiency in insulin and decrease or loss of insulin activity results in hyperglycemia." (PMID 34068827, 2021). "Contrary to our results, a dietary dose of GSPE (25 mg/kg BW) managed to reduce the plasma levels of triglycerides, glucose, and insulin in cafeteria-diet-fed male rats, while puerarin, resveratrol, and procyanidin B2 ameliorated hyperglycaemia and hyperinsulinemia caused by an obesogenic diet." (PMID 34208508, 2021). "Clinically, type 1 diabetes is characterized by a typical autoimmune assault against the β-cells, inducing progressive β-cell death which is in line with the progressive decline in first-phase insulin secretion and causes insulin insufficiency and hyperglycemia." (PMID 34055984, 2021). "This is associated with insulin dysfunction, insulin resistance and ensuing hyperglycaemia." (PMID 34940355, 2021). "The insulin that is produced has the function of regulating carbohydrate metabolism, and its absence causes glucose to remain in the bloodstream, thus characterizing a state of hyperglycemia." (PMID 34190871, 2021). "However, chronic exposure to excessive fuel intake, especially hyperglycaemia, has deleterious effects on beta cells, leading to their dysfunction and insufficient insulin secretion and eventually to their failure, loss, and insulin deficiency." (PMID 34680532, 2021). "There is an ongoing secondary analysis of the effect of acute insulin therapy on the risk of HT, which may provide further insights into the link between hyperglycemia and HT from the SHINE trial." (PMID 34054705, 2021). "In Langerhans Islets from obese mice which differed in their degree of hyperglycemia and in liver fat content a semi-explorative approach identified 497 differentially expressed and methylated genes linked to insulin secretion and extracellular matrix-receptor interaction." (PMID 34140928, 2021). "It has been reported that oxygen delivery inadequate to fulfill the metabolic needs of the patient is one of the factors promoting hyperlactatemia during CPB, which is associated with reactive hyperglycemia that is probably due to insulin resistance triggered by catecholamine release." (PMID 34879822, 2021). "Interestingly, this confirms that administration of high-dose corticosteroids is an unlikely cause of donor hyperglycaemia necessitating insulin therapy." (PMID 33665687, 2021). "Overall, the findings suggest that hyperglycaemia may be responsible, at least in part, for the abnormal skeletal growth associated with impaired insulin signalling in adulthood." (PMID 34708692, 2021). "Furthermore, hyperglycemia and angiotensin II type 1 receptor-induced proinflammatory cytokines in human islets cause impaired insulin secretion and inflammation." (PMID 34206537, 2021). "Indeed, activation of AMPK prevented hyperglycemia in insulin-resistant, leptin-deficient mice, and improved glucose tolerance in insulin-resistant Zucker rats." (PMID 34831343, 2021). "We hypothesised that neonatal hyperglycaemia would be associated with worse neurodevelopmental outcomes, while insulin treatment would be associated with better neurodevelopmental outcomes." (PMID 33863775, 2021). "Reductions in bone mass in individuals with type 1 diabetes has been shown to result from the diminished secretion and/or action of insulin, which is associated with the formation of advanced glycation end-products (AGEs), induced by oxidative stress and hyperglycemia." (PMID 34440530, 2021). "In hyperglycemia conditions, FoxO1 could be found in nucleus or even losing its expression, to response oxidative stress, which is associated with the loss of insulin secretion." (PMID 33686020, 2021). "The possible mechanisms underlying hyperglycemia are due to impairment of insulin action and insulin resistance, or may be due to certain defects of metabolic pathways leading to either glycogenesis decrease or accelerated glycogenolysis." (PMID 34970218, 2021).
Hyperglycemia (continued). "First, as a result of reduced insulin tolerance, subsequent hyperglycemia, prediabetes patients may be at risk for cardiovascular disease." (PMID 33750338, 2021). "The overdose of insulin can lead to severe hypoglycemia, causing seizures, coma, and even death; or under dosing of insulin may result in hyperglycemia and sometimes ketoacidosis." (PMID 34924015, 2021). "Our results also demonstrate that hepatic Sam68 deficiencies improve insulin sensitivity and reduce hyperglycemia in diabetic mice, which suggests that Sam68 could be a therapeutic target for the treatment of T2D." (PMID 34099657, 2021). "Previous research found that the mechanism underlying the increased blood insulin levels during hypoxic conditions could be explained by hyperglycemia induced by elevated cortisol levels." (PMID 33532907, 2021). "Furthermore, insulin sliding scale has been shown in some studies to increase the risk of both hyperglycaemia and hypoglycaemia." (PMID 34277991, 2021). "The association of the start of insulin therapy with improved health status and psychosocial functioning might be the effect of the diminishing symptoms of hyperglycemia." (PMID 33776906, 2021). "Although hyperglycemia is associated with worse outcomes after aneurysmal subarachnoid hemorrhage (aSAH), there is no consensus on the optimal glucose control metric, acceptable in-hospital glucose ranges, or suitable insulin regimens in this population." (PMID 33420311, 2021). "However, improper dosing of insulin puts patients at risk of life‐threatening hypoglycemia and a myriad of long‐term complications resulting from prolonged hyperglycemia." (PMID 34387389, 2021). "Interestingly, fasting-induced autophagy was associated with increased insulin secretion and mitigated hyperglycemia." (PMID 34698133, 2021). "Ferulic acid regenerated pancreatic beta-cells, reduced the risk of high-fat diet-induced hyperglycemia via insulin secretion and hepatic glucose-regulating enzyme activities, and regulated blood glucose levels by elevating glucokinase activity and production of glycogen." (PMID 34776975, 2021). "Sesquiterpenoids have shown potent antidiabetic activity via various mechanisms such as inhibition of enzymes involved in hyperglycemia, protecting β-pancreatic cells, preventing oxidative and inflammatory damages associated with the disease, and improving insulin secretion." (PMID 34285703, 2021). "Stress hyperglycemia is mediated by the hypothalamic–pituitary–adrenal axis, the sympatho-adrenal system, and pro-inflammatory cytokines that cause a stress response with excessive gluconeogenesis, glycogenolysis, and insulin resistance." (PMID 34659090, 2021). "Furthermore, several studies have reported that changes in the metabolic state, including blunt insulin sensitivity and hyperglycemia, are directly linked to the onset and development of dementia, especially memory deficits." (PMID 33945675, 2021). "Indeed, IRE1α-deficient β-cells and mice demonstrate hyperglycemia and hypoinsulinemia and impaired insulin production, which recapitulates the GLT effect on cultured β-cells and islets, which we observed." (PMID 34944536, 2021). "It is suggested that hyperglycemia (HG), a typical marker of diabetes causing nutrient stress, may alter the production of adipocytokines and change biochemical pathways including insulin signaling." (PMID 34299331, 2021). "The daily necessity to inject exogenous insulin to treat hyperglycemia leads to a relative portal vein insulin deficiency and potentiates hypoglycemia which can induce weight gain, while daily fluctuations of blood sugar levels affect the hepatic glycogen storage and overall metabolic control." (PMID 34759828, 2021). "The fear of hypoglycaemia may drive patients and care providers to lower the insulin dosage, eventually causing prolonged hyperglycaemia when the insulin needs increase." (PMID 33099763, 2021).
Hyperglycemia (continued). "Resistance to insulin causes dyslipidemia, hyperinsulinemia, hypertension, and hyperglycemia." (PMID 33995826, 2021). "The increase in glucose concentrations in the bloodstream (hyperglycemia) may be associated with the inability to produce, secrete, or fail to absorb insulin, or even with a set of all these abnormalities." (PMID 34366888, 2021). "This notion is supported by evidence demonstrating that chronic hyperglycemia is associated with smaller exercise-induced improvements in peripheral insulin sensitivity, which in turn was linked with blunted exercise-induced improvements in postprandial glucose response." (PMID 33178135, 2020). "The purpose of this study was to investigate the effect of metabolic and weight change induced by insulin treatment on DPN measures in a rat model of T2D to elucidate the importance of hyperglycemia as a driving factor of DPN versus other risk factors also affected by insulin treatment." (PMID 32832565, 2020). "However, once ß-cells start malfunctioning, the fall of compensatory insulin secretion will cause hyperglycemia." (PMID 32183037, 2020). "However, insulin insensitivity, and impaired glucose uptake, typically accompanies hyperglycemia-associated delirium." (PMID 32513828, 2020). "This can cause variations in insulin absorption, which may cause hypoglycemia or hyperglycemia to the patient." (PMID 33029335, 2020). "Hence, the paradoxical induction of glucagon secretion is due to direct effects of hyperglycemia in the alpha-cell and it is exacerbated indirectly by loss of beta-cells, when the inhibitory paracrine effect of insulin is lost." (PMID 32132928, 2020). "Thus, deficiency of ID1 gene increased insulin secretion to protect against hyperglycemia in an animal model." (PMID 32481541, 2020). "However, long-term IR or hyperglycemia can cause irreversible damage to islet cells and lead to a complete failure of insulin secretion, which is an important feature of T2DM progression." (PMID 33381036, 2020). "Even though independent associations among hyperglycemia, ROP, and IGF1 have been described, a more detailed understanding of ROP risk, with specific levels of hyperglycemia during different postnatal weeks, the contribution of insulin insensitivity, and the role of IGF1, is needed." (PMID 33004691, 2020). "Inadequate insulin levels cause hyperglycaemia, as glucose production exceeds utilisation." (PMID 32533229, 2020). "It is uncertain whether the beneficial effects of metformin are due to a direct effect or the results of improved insulin sensitivity, weight loss and improved hyperglycemia." (PMID 32467714, 2020). "Thus, infants born before 28 weeks gestation are at a developmental stage when insulin resistance, although physiologic in utero, puts them at risk for transient hyperglycemia after birth." (PMID 33004691, 2020). "Therefore, mimicking the dynamic release of insulin is critical to avoid extended tissue exposure to hyperglycemia or the adverse risk of hypoglycemia." (PMID 32325974, 2020). "The disease is characterized by the T cell-mediated destruction of the insulin producing beta cells in the pancreas, leading to impaired insulin secretion, hyperglycemia, and increased risk of both acute and chronic complications associated with significant morbidity and mortality." (PMID 32725277, 2020). "Acute hyperglycemia, which upregulates adiponectin secretion and/or exogenous insulin administration, may have caused the decrease in adiponectin levels." (PMID 31905496, 2020). "Furthermore, the insufficient insulin secretion due to hyperglycemia caused reduced T4 to T3 conversion and increased conversion of T4 to 3,3′5′ ́-triiodothyronine (an inactive form of T3), both resulting in decreased levels of FT3." (PMID 32714391, 2020).
Hyperglycemia (continued). "This change may be due to an inhibited upregulation of adiponectin secretion and/or a blunted suppressive effect of insulin due to hyperglycemia or exogenous insulin administration may have caused the decrease in adiponectin levels." (PMID 31905496, 2020). "The precise mechanisms underlying gestational diabetes remain unknown although the hallmark of the disease was found to be hyperglycaemia due to increased insulin resistance." (PMID 32855973, 2020). "Regards to energy metabolism, the hyperglycaemia and hyperinsulinemia observed in insulin resistant patients are also associated to elevated risk of cancer and a widely known mechanism of increasing insulin sensitivity and glucose uptake is upregulating AMPK activity." (PMID 33371214, 2020). "Looking into preferred term level for each drug class, women dominated the reports of class-specific AEs of newer antidiabetic drugs such as urinary tract/genital infection (all reported by women) in SGLT2i, edema in TZD (risk ratio (RR) 12.56), and hyperglycemia in insulin users (RR 15.35)." (PMID 33067519, 2020). "A simple feedback model cannot adequately capture the two effects of hyperglycemia underlying the paradoxical increase of glucagon secretion, because it is centered on negative control loops between glycemia and two pancreatic hormones, insulin and glucagon." (PMID 32132928, 2020). "INS gene mutation resulted in insufficient insulin secretion that leads to hyperglycemia." (PMID 32699230, 2020). "In addition, GLUT2 dysfunction in the liver can lead to hyperglycemia due to decreased response and sensitivity of hepatocytes to insulin signaling, causing a decreased inhibition of glucose production." (PMID 32877990, 2020). "Surprisingly, the survival rate of insulin-deficient RIP-CreΔLEPR mice administered leptin (RIP-CreΔLEPR-LEP) was comparable to insulin-deficient WT mice administered leptin (WT-LEP) despite hyperglycemia." (PMID 33071988, 2020). "However, it is possible that since this study showed that probable sepsis was a risk factor for neonatal hyperglycaemia, serum insulin was most likely elevated as a compensatory mechanism to correct hyperglycaemia in those babies." (PMID 32637004, 2020). "Also, because there is elevated counter-regulatory hormones which is thought to be responsible for stress hyperglycaemia, there is associated relative insulin resistance." (PMID 32637004, 2020). "We hypothesized that exposure to hyperglycemia was independently associated with severe ROP and that insulin therapy, a marker of an attempt to control hyperglycemia, would be associated with less frequent ROP." (PMID 33306685, 2020). "Postprandial hyperglycaemia can occur in adulthood and is likely to be associated with recurrent pancreatitis and hypertriglyceridaemia, which lead to insulin secretion impairment or an adaptive mechanism of the glucose receptor, GLUT2, for reducing the secretion of insulin." (PMID 33179602, 2020). "Notably, the role of other pathways, that are implicated in the development of hyperglycaemia, including pancreatic secretion of insulin, glucagon, lipolysis, glucose uptake, renal absorption, neurotransmitter signaling, etc cannot be ruled out." (PMID 33088930, 2020). "Overcoming hyperglycemia by enhancing chromium reabsorption in obese mice may cause chromium to move to the metabolic tissue and contribute to activating insulin signaling." (PMID 32260278, 2020). "Taken together, intensive insulin treatment is essential for preventing diabetic complications caused by hyperglycemia, but it is associated with adverse effects, such as weight gain, hypoglycemia, and hyperglycemia, which cause low compliance leading to glycemic variability." (PMID 32973680, 2020). "Moreover, a transgenic mice model expressing human IAPP (hIAPP) spontaneously developed amyloidosis, showing impaired insulin production, β-cell loss, and fasting hyperglycemia." (PMID 32265649, 2020).